IL1B (interleukin 1 beta)
Diseases named in the same sentence as IL1B in open-access papers (continued):
Sharing a sentence is not in itself a finding about the gene and the disease.
tumor (continued). "NLRP3 inflammasome activation and IL-1β secretion play a critical role in promoting tumor growth and metastasis in BC and they are associated with tumor proliferation, angiogenesis, invasiveness, relapse and progression." (PMID 33014808, 2020). "An increased proportion of ILC2s have been also found in pancreatic adenocarcinoma where tumor cells and tumor cell-conditioned macrophages produce IL-1α and IL-1β favoring TSLP secretion by cancer-associated fibroblasts." (PMID 33233582, 2020). "The majority of tumor-associated macrophages (TAMs) expressed proinflammatory cytokine/chemokine genes, such as IL1B, CCL2, CCL3, and CCL20." (PMID 33277616, 2020). "Subsequently, it was shown that breast cancer cells that expressed high levels of G-CSF and IL-1β exhibited high neutrophil counts and tumor-associated thrombosis, which was dependent on NET formation." (PMID 32849639, 2020). "Taken together, our data underline the role of IL-1β as a hub of inflammatory signaling within the tumor microenvironment that drives the tumor-promoting crosstalk between GBM and adaptive immune cells, and thus promotes GBM aggressiveness." (PMID 32069807, 2020). "Our data suggest that the effect of Nigericin on tumor survival will depend on the balance between pyroptosis and survival associated with IL-1β release." (PMID 33613529, 2020). "The anti-tumor efficacy of this Lipid A has previously been demonstrated in several models of tumors and was dependent on cytokine secretion (IFNγ, IL-1β and TNFα), iNOS activation and tumor-associated neutrophil (TAN) reprogramming into anti-tumorigenic N1." (PMID 32370259, 2020). "Meanwhile, the tumor-promoting effects of M2 macrophages induced by lung cancer microparticles are associated with increased IL-1β secretion after macrophages sense the non-coding RNA in TMPs through the TLR3 signaling pathway." (PMID 32983146, 2020). "Analysis of resected tumour specimens demonstrated that that intratumoural levels of IL‐8, IL‐1β and TNFα were associated with larger tumours and poor differentiation." (PMID 32458441, 2020). "In turn, TSLP was secreted by cancer-associated fibroblasts (CAFs) activated by IL-1α and IL-1β, which are products of cancer cells and tumor cell-conditioned macrophages." (PMID 33022971, 2020). "IL-1β is increased in a variety of tumors and its expression is associated with the tumor development and progression 13, 15-17." (PMID 32547321, 2020). "Here, we revealed the underlying mechanism of IL-1β-promoted tumor cell stemness by studying BMP1/5/8 and ID1 signaling pathway, but not TGF-β/Smad2/3 signaling pathway." (PMID 32547321, 2020). "Increased IL-1β levels in the tumor environment have been related to a worse outcome of patients, supporting its central role in inflammation-associated tumor progression." (PMID 33014808, 2020). "Pro-inflammatory cytokines (TNF-α and IL-1β) induced by tumor-associated immune cells play crucial roles in the migration and differentiation of MSCs within the tumor." (PMID 32121074, 2020). "Accumulation of tumor-infiltrating macrophages with activated NOD-like receptor C4 (NLRC4) inflammasomes in the obese tumor microenvironment has been linked to increased IL-1β activation." (PMID 33604295, 2020). "In another report, LPS/S1PR1 signaling participates in NLRP3 expression and IL-1β production in tumor-associated macrophages." (PMID 32695095, 2020). "TNF-α, IL-6 and IL-17 have known roles in tumor growth and promotion; IL-6 and IL-10 are produced by tumor-associated macrophages and create conditions of immune suppression and angiogenesis; IL-1β and IL-6 promote angiogenesis and tumor invasion." (PMID 33396710, 2020).
tumor (continued). "The NLRP3/IL-1β pathway is required for the deleterious effects of 5-FU and gemcitabine on tumor immune response, as tumor growth is inhibited in mice deficient for NLRP3, or IL-1R." (PMID 32635472, 2020). "TNF-α and IL-1β, the major proinflammatory cytokines associated with systemic inflammation, play a critical role in tumorigenesis, tumor progression, and carcinogenesis." (PMID 33050597, 2020). "Inhibition of C1-inh in rats with GBM, using appropriate antibodies, was found to increase survival but also led to decreased levels of cytokines IL-1β and GM-CSF, which are associated with an immunosuppressive tumor microenvironment." (PMID 32765498, 2020). "High IL-1β content is associated with tumor invasiveness, migration, and more aggressive tumor phenotype." (PMID 30642137, 2019). "In pancreatic ductal adenocarcinoma, constitutive NF-kB activity in both CAFs and tumor cells is sustained by a positive mutual loop involving secreted IL-1β and the cognate receptor IL-1 receptor–associated kinase 4 (IRAK4), expressed on both cell types." (PMID 30927908, 2019). "The regulatory mechanisms underlying the maturation and secretion of IL-1β and IL-18 into the tumor microenvironment require profound elucidation." (PMID 31492049, 2019). "A particularly intriguing NFκB target gene encodes pro-IL-1β, which is processed by caspase-1 or neutrophil protease to the key proinflammatory and tumor-promoting cytokine IL-1β." (PMID 31766169, 2019). "Similar to TAMs, it is likely that MDSCs are stimulated by a variety of soluble factors, such as GM-CSF, VEGF, TNF-α, PGE2, IL-1β, IL-6, and IL-10, which are secreted by tumor and infiltrating immune cells, as well as tumor-associated fibroblasts." (PMID 31428574, 2019). "Inhibition of IL-1β in mice treated with S.t-ΔpGlux/pT-ClyA using an IL-1β antibody caused tumor growth to resume." (PMID 31754923, 2019). "Tumor cells showing BRAF V600E mutation tend to have increased cytokine secretion such as that of interleukin (IL)-1β, IL-6, and IL-8, because cytokines such as tumor necrosis factor alpha or IL-1β increase ATX and LPA levels." (PMID 31455351, 2019). "MDSCs are associated with inflammation-induced tumor progression, as they are activated by pro-inflammatory IL-1β that subsequently induces a tumor-promoting IL-10-dominated environment and an anti-inflammatory (M2) macrophage response." (PMID 31396229, 2019). "IL‐1β, as a pro‐inflammatory cytokine, is often associated with tumor invasion and metastasis closely." (PMID 31222982, 2019). "Tumor-derived interleukin-1β (IL-1β) has recently been implicated in the systemic increase in G-CSF expression by supporting IL-17 expression by gamma delta T cells." (PMID 31552036, 2019). "High tumor gene expression of IL-1β was associated with a more favorable overall survival in cetuximab-treated HNSCC patients but not in non-cetuximab-treated patients." (PMID 31346466, 2019). "IL‐1β is a pleiotropic cytokine implicated in tumor progression through effects on proliferation, invasion, metastases, myeloid cell recruitment, and angiogenesis." (PMID 31297985, 2019). "In the context of primary tumor growth and metastasis, IL-1β has been associated with the infiltration of myeloid-derived suppressor cells (MDSCs) and tumor-associated macrophages in the tumor microenvironment." (PMID 31552036, 2019). "TNBC tumor irradiation in a mouse model significantly increased the plasma level of IL-1β, which was associated with lung metastases." (PMID 30728901, 2019). "Our data reveal the association between genetic polymorphisms of IL‐1 and BC susceptibility in the Chinese Han population and indicates that IL‐1 polymorphisms are closely associated with tumor markers and IL‐1β protein expression in BC patients." (PMID 31297985, 2019). "Compared with the ER+BCC-NAF organoid co-cultures, the tumor-associated CD45+CD31+ cells secrete 5.7 ± 0.48-fold more IL1β, 1.5 ± 2-fold CCL7, 1.2 ± 0.2-fold IL6, and 1.1 ± 0.02-fold IL8." (PMID 31419632, 2019).
tumor (continued). "Compared with that in the PBS control, IL-1β caused increased peritoneal metastases and a higher tumour burden." (PMID 31588122, 2019). "Although high levels of IL-1β have been associated with tumour progression, a recent study has suggested that physiological levels of IL-1 are essential for antitumor immunity." (PMID 30538296, 2019). "Inhibition of the NLRP3 inflammasome was seen to reduce tumor burden in the murine model of colitis-associated cancer, with the increased tumor burden correlating with attenuated levels of IL-1β and IL-18 at the tumor site." (PMID 31231372, 2019). "Another important inflammatory mediator, IL-1b, which is released by tumor stromal cells or cancer-associated macrophages, has also been demonstrated to trigger inflammation and enhance lymphangiogenesis in tumors." (PMID 31390756, 2019). "Further, cytokines secreted by adipose tissue like IL-1β, IL-6 and IL-8 have been implicated in tumor progression by stimulating tumorigenic pathways in cancer cells, such as TNFα and NF-κB signaling." (PMID 29930291, 2018). "The end targets of this pathway, IL-6, IL-1α and IL-1β, and IL-8 cytokines, presented increased expression in the mesenchymal subtype, and they have also been associated to tumor malignancy and tumor cell migration." (PMID 29912993, 2018). "Using genetic mouse models as well as agents for pharmacological inhibition of IL-1 signaling therapeutically applied for treatment of IL-1 associated autoimmune diseases indicate that IL-1β is a driver of tumor induction and development." (PMID 30042333, 2018). "Although studies manipulating tumor-associated monocytes/macrophages show only small increases in M1-like cytokines and chemokines (such as TNFα, IL1β etc.), the greatest increase was seen following monocyte-specific NRP1 ablation." (PMID 30479695, 2018). "In that model, desmoplasia is encouraged by the activation of pancreatic stellate cells, which occurs with the recruitment of tumor-associated neutrophils by adipocyte-secreted IL-1β." (PMID 29723245, 2018). "A dysregulated expression of IL-1β has been linked to tumor development and growth in different types of cancer including CRC." (PMID 30619282, 2018). "IL-1β generated by tumor cells and by tumor-associated macrophages in an autocrine manner induced CCL2 secretion which in turn attracted macrophages." (PMID 29983861, 2018). "IL-1β is a tumor-associated factor leading to expansion and migration of MDSC, being regulated by the IL-1RI/NF-κB pathway." (PMID 30042333, 2018). "Although tumor-associated macrophages have characteristics of the M2-like phenotype, this cell population can also produce pro-inflammatory cytokines, such as IL-1β, depending on the conditions of the tumor microenvironment." (PMID 30586442, 2018). "MDSCs are a heterogeneous population of cells that can be induced by tumor-associated inflammation, including autoimmune related cytokines such as IL-1β and IL-6." (PMID 29643991, 2018). "In particular, IL-1β exhibits an essential role in inflammation-associated carcinogenesis and supports tumor growth and metastasis." (PMID 29854832, 2018). "Elevated IL1B levels in tumor and serum are associated with higher tumor grade and increased invasion in breast and pancreatic cancer and in myelogenous leukemia, and are correlated with poor patient outcome." (PMID 28143606, 2017). "Sustained production of pro-inflammatory cytokines, such as TNF-α, IL-6 and IL-1β, results in chronic inflammation, which, in turn, increases cancer risk, tumor development and progression." (PMID 29044191, 2017). "NGF caused a considerable increase in the level of TNF-α and IL-1β in the serum of the tumor-bearing mice." (PMID 28878143, 2017). "Previous clinical studies also reveal that increased IL-1β in tumor tissues is associated with poorer prognosis." (PMID 28955343, 2017).
tumor (continued). "High levels of IL-1β in tumor and serum are associated with higher tumor grade and increased invasion in breast, pancreatic cancer and myelogenous leukemia, and are also correlated with poor patient outcome." (PMID 28927416, 2017). "Consistent readings were obtained for the following analytes: RANTES, MCP-1, G-CSF, GM-CSF, IL-8, IL-1β, INFα2, and IL12p70, all related to inflammatory processes, although only the first six have been previously associated with pro-tumor effects." (PMID 28337194, 2017). "By contrast, FLX administration was associated with lower serum IL-1β compared to untreated tumour mice." (PMID 28120908, 2017). "CSF-1 influences also the maturation of tumor-associated macrophages; in CSF-1 deficient animals macrophages remained more immature with lower expression of IL-1β, TNF-α." (PMID 28197019, 2017). "In this study, we reveal that inflammatory niches consisting of tumor-associated macrophages and fibroblasts contribute to treatment tolerance through a cytokine-signaling network that involves macrophage-derived IL-1β and fibroblast-derived CXCR2 ligands." (PMID 28450382, 2017). "High levels of IL-1β in the tumor microenvironment are directly associated with a poor prognosis mainly because IL-1β promotes tumor invasiveness by angiogenesis induction and the activation of myeloid-derived suppressor cells and M2 macrophages." (PMID 29113423, 2017). "Stimulation of MDA-MB-231 and MCF7 tumour cells with IL-1β caused a significant increase in migration, observed from 2 h in MDA-MB-231 cells and from 24 h in MCF7 cells." (PMID 28551814, 2017). "Tumor-associated macrophages and myeloid suppressive cells represent tumor-promoting immune cells together with their derived cytokines IL-6, IL1β, IL23 and TNFα." (PMID 27608835, 2016). "Primary and metastatic tumor tissues were associated with elevated levels of IL-1β, which potentially induces a number of cytokines, chemokines and transcription factors in both myeloid cells and tumor cells." (PMID 27786298, 2016). "In this context, the outcome can then be different since in certain experimental settings this activity is protective against cancer development, while in other settings NLRP3 activation and IL-1β secretion are associated to a more malignant tumor phenotype." (PMID 27221966, 2016). "Compared to WT cells, CD11b cells from tumor tissues of caspase-1 deficient mice secreted significantly less IL-1β." (PMID 27786298, 2016). "The expressions of TNF‐α, MMP9, HIF‐α, VEGF, NF‐κB, and IL‐1β were associated with the infiltration of inflammatory cells and the inhibition rate of tumor cells." (PMID 27734611, 2016). "With respect to IL-1β, this pro-inflammatory cytokine has been associated with angiogenesis, invasiveness of different tumor cells and increased risk of CRC." (PMID 27092172, 2016). "Some mechanisms responsible for dysfunction of immune cells are directly mediated by factors produced by tumors, whereas others result from tumor-associated microenvironment, including IL-1β, IL-4, IL-6, IL-10, IFN-γ and TGF-β." (PMID 27391078, 2016). "We found that tumor progression was associated with the activation of inflammasome and elevated levels of IL-1β at primary and metastatic sites." (PMID 27786298, 2016). "In the tumor, IL-1β, probably produced by tumor-associated macrophages, was shown to be critical for the expansion of memory Th17 cells in ovarian and breast cancers." (PMID 26583099, 2015). "Of these 5, adenosine was also lower in obese and in tumor-bearing mice (p<0.05) and its concentration was inversely associated with colonic Il1b and Tnf production (p<0.05)." (PMID 26284788, 2015). "Nuclear shuttling of YBX1 has been associated with its increased tumor promoter activity, and has been shown to occur upon stimulation with IL-1β." (PMID 26318844, 2015). "M1 macrophages with TNF-α/IL-1β production and an active NF-κB pathway are central to tumor causal inflammation and play an important role in tumorigenesis." (PMID 26684869, 2015).
tumor (continued). "The presence of tumor-associated macrophages (TAMs) and high serum levels of IL-1β in RCC patients correlate with advanced disease." (PMID 26486078, 2015). "Parabecteroides distasonis was lower in tumor-bearing mice and its abundance was inversely associated with colonic Il1b production (p<0.05)." (PMID 26284788, 2015). "Production and secretion of IL-1β are associated with pain in pathological conditions like tumor growth." (PMID 26538839, 2015). "High expression of some interleukins, such as IL-1α and IL-1β, has been associated with a more aggressive tumor type and poor prognosis." (PMID 24887580, 2014). "IL-1β upregulates a variety of processes that contribute to higher angiogenesis, tumor growth, and tumor progression and is considered a strong and causative pro-inflammatory factor whose expression is associated with advanced cancer." (PMID 25566498, 2014). "The STAT3 pathway is more highly activated in response to several cytokines, including IL-1β, IL-4 and IL-10 in tumor-associated macrophages of the M2 phenotype than in M1 macrophages." (PMID 25198511, 2014). "Tumor-driven myeloid expansions are linked to the local inflammatory environment and engineered expression of GM-CSF or IL-1β by cancer cells has been shown to drive myeloid expansion." (PMID 23936036, 2013). "In concert with these data, IL-1β- and IL-1α-deficient mice had decreased tumor numbers and tumor size in the MCA model of fibrosarcoma." (PMID 24273542, 2013). "The association between therapeutic induction of IL-1β and neutrophil recruitment cannot be demonstrated because the collection of primary tumour biopsies from patients who had recently undergone treatment is not ethical and would not be allowed." (PMID 23065753, 2012). "We showed that both HCT116 and Hke-3 cells induced IL1β in peripheral blood monocytes, precursors of the tumor associated macrophages." (PMID 23029025, 2012). "Aberrant production and signaling of IL-1β are tightly linked to tumor generation, growth and metastasis in multiple types of cancers." (PMID 23174018, 2012). "Together, these data established that tumor associated macrophages protect tumor cells from TRAIL-induced apoptosis in an IL-1β dependent manner." (PMID 20661477, 2010). "These experiments revealed that IL-1β deficient macrophages fail to protect tumor cells from TRAIL-induced apoptosis." (PMID 20661477, 2010). "Upregulation of metastasis and tumor angiogenesis by IL-1β as observed in those studies was associated with increased activity of matrix metalloproteinases and expression of the pro-angiogenic molecule hepatocyte growth factor." (PMID 18801189, 2008). "Tumour tissue cytokine concentrations are elevated compared with healthy controls and IL-1β concentrations are positively associated with some markers of systemic inflammation." (PMID 17088911, 2006). "Additionally, IL-1β recruits neutrophils and monocytes and stimulates the differentiation of tumor-associated macrophages (TAMs) with immunosuppressive and proangiogenic phenotypes." (PMID 41596738, 2026). "Additionally, microbial dysbiosis has been linked to the activation of γδ T cells via an IL-1β/IL-23-dependent mechanism, leading to IL-17 secretion, neutrophil infiltration, and sustained inflammation within the tumor microenvironment." (PMID 41486167, 2026). "Therefore, in myeloid cells, PEFs primarily modulate MDSCs through the NLRP3/IL-1β signaling pathway and regulate tumor-associated macrophages via the CCLs/CCR2 signaling axis." (PMID 41357174, 2025). "For instance, for tumors routinely identified as immunologically cold —harboring either few or exhausted immune cells—IL-1β is likely to exert additional effects through the activation of signaling pathways in bystander normal cells inhabiting the tumor-associated tissue microenvironment." (PMID 39858071, 2025).